SAXO4 (stabilizer of axonemal microtubules 4)
Synonyms: C11orf66; PPP1R32; IIIG9; FLJ32771
Tractability: Antibody: the Human Protein Atlas places it where antibodies can reach.
Gene: Protein-coding gene on chromosome 11 (61,481,120 to 61,490,931, forward strand). Ensembl gene ENSG00000162148.
Subcellular location: Cell projection, cilium; Cytoplasm; Cytoplasm, cytoskeleton, flagellum axoneme
Subcellular location (Human Protein Atlas): Plasma membrane; Cytosol; End piece; Mid piece; Nucleoplasm; Principal piece
Gene Ontology:
Molecular function: phosphatase binding; protein binding
Biological process: flagellated sperm motility
Cellular component: ciliary basal body; axonemal A tubule inner sheath; cytoplasm; sperm flagellum; cilium
Genetic constraint (gnomAD): Loss-of-function variants: 43 observed, 56.46 expected, observed/expected ratio (o/e) 0.76, 90% interval 0.6 to 0.98. The upper end of that interval is the gene's LOEUF score, 0.98, which puts it in group 4 of 6, group 1 being the genes least tolerant of losing a copy. Missense variants: 542 observed, 573.84 expected, observed/expected ratio (o/e) 0.94, 90% interval 0.88 to 1.01. Synonymous variants: 206 observed, 227.64 expected, observed/expected ratio (o/e) 0.9, 90% interval 0.81 to 1.02.
Homologues: Orthologues: macaque SAXO4 (95% identical), dog SAXO4 (77% identical), rat Saxo4 (73% identical), mouse Saxo4 (72% identical), guinea pig SAXO4 (64% identical), rabbit SAXO4 (64% identical), chimpanzee SAXO4 (51% identical), tropical clawed frog saxo4 (35% identical).
Diseases named in the same sentence as SAXO4 in open-access papers:
SAXO4 is named in the same sentence as 12 diseases in open-access papers, as found by Europe PMC text mining. Sharing a sentence is not in itself a finding about the gene and the disease.
SAXO4 shares sentences with these, for which no sentence is quoted: Hydrocephalus (2 papers); alcoholism (1); anaplastic ependymoma (1); brain tumors (1); cancer (1); ciliopathies (1); colon cancer (1); ependymoma (1); nanophthalmos (1); osteosarcoma (1); tumor (1); Ventriculomegaly (1).